SPHK1 (sphingosine kinase 1)
Diseases named in the same sentence as SPHK1 in open-access papers (continued):
Sharing a sentence is not in itself a finding about the gene and the disease.
tumor (continued). "Patients were separated in two groups according to the proportion of tumor cells positive for SPHK1 mRNA (Low SPHK1: ≤ 50% tumor cells positive and High SPHK1: > 50% tumor cells positive)." (PMID 31974367, 2020). "Sphingosine kinase 1 (SphK1) is mainly localized in the cytosol and generates S1P that is transported outside the cell to the extracellular space including the tumor microenvironment." (PMID 32456134, 2020). "Consistently, the growth of B16F10 tumours is impaired in SphK1−/− mice as compared to wild-type animals." (PMID 32858889, 2020). "S1P in the tumour microenvironment is secreted and released by apoptotic tumour cells due to SPHK1 activation." (PMID 32155312, 2020). "As compared with vehicle control tumors, Akt inactivation and SphK1 inhibition were also detected in I-BET726-treated tumor tissues." (PMID 32371868, 2020). "Stimulation of SPHK1/S1P/S1P3 by environmental carcinogens promoted CSC-induced tumor metastasis in vivo; while knockdown of S1P3 reduced the CSC population in MCF-7 cells." (PMID 32260399, 2020). "Tumour growth was significantly slower upon adoptive transfer of pMel-SphK1−/− T cells, as compared to mice injected with wild-type pMel T cells." (PMID 32858889, 2020). "The levels of Sphingosine Kinase 1 (SPHK1) were also found to be significantly upregulated in tumor tissues in both the cohorts." (PMID 32170160, 2020). "A significant upregulation in the expression of CERK and SPHK1 was observed in tumor tissues in local and TCGA cohort." (PMID 32170160, 2020). "Downregulation of BRD4-regulated proteins and inhibition of the SphK1-Akt signaling were detected in I-BET726-treated A431 xenograft tumor tissues." (PMID 32371868, 2020). "Attenuation of SPHK1 activity contributes significantly to macrophage pyroptosis and tumor inhibition." (PMID 33123153, 2020). "Another SphK1 inhibitor SKI-5C significantly reduced the growth of tumours from TNBC cell line MDA-MB-231 in xenografted SCID mice." (PMID 31752564, 2020). "In a mouse BC xenograft model, BBP increased the incidence of lung metastasis and this effect was reversed with SPHK1 or S1PR3 knockdown tumor cells." (PMID 33203443, 2020). "In this study, the relationship of sphingosine kinase 1 on pyroptosis as it provides a new strategy for tumor therapy was discussed." (PMID 33123153, 2020). "To explore the role of SPHK1 in POTEE-mediated tumor promoting functions, we firstly transfected gradient increased doses of POTEE-expressing recombinant lentivirus or POTEE-targeting shRNA into HCT15 and SW480 cells, respectively." (PMID 31723122, 2019). "Growing evidence shows that tumor cells upregulate SPHK1 expression to release more S1P into the tumor microenvironment." (PMID 31101115, 2019). "IHC analysis of 88 FMT cases revealed that the expression level of SPHK1 was upregulated in 53 tumor tissues (60.2%) compared to adjacent mammary tissues." (PMID 31101115, 2019). "Injection of hispidulin in xenograft nude mice in a dose-dependently inhibited tumor size and decreased SphK1 activity, as well as an increase of ceramide accumulation in tumor tissues." (PMID 32009958, 2019). "There is growing evidence that SPHK1 activation promotes oncogenic transformation, tumor growth, chemotherapy resistance, and metastatic spread." (PMID 31101115, 2019). "Some studies demonstrated that tumor tissues contain significantly more SphK1 than normal colonic mucosa." (PMID 30684960, 2019). "Subsequently, sphingosine is phosphorylated by sphingosine kinase 1 (SPHK1) or 2 (SPHK2) to form a tumor promoter, S1P." (PMID 29805753, 2018). "Further, expression of p16 mRNA, a marker of senescent cells, was increased in SphK1−/− tumor tissues compared to WT tumors." (PMID 29643998, 2018). "Intriguingly, the proportion of reduction caused by SphK1 deficiency was not changed during the course of experiments, suggesting that less tumors in SphK1−/− mice is likely attributable to the inhibition of tumor initiation." (PMID 29643998, 2018).
tumor (continued). "For instance, it promotes tumor progression and metastasis through the miR-200a-3p/ZEB1 signaling pathway and promotes tumor angiogenesis in liver cancer through miR-107/E2F1/SPHK1 signaling." (PMID 29495592, 2018). "Remarkably, although primary liver tumor cells from both WT and SphK1−/− underwent cell death, there was significantly more death in the SphK1−/− tumor cells as fewer colonies of cells were formed from SphK1−/− tumor cells than WT tumor cells." (PMID 29643998, 2018). "Tumor cells benefit from this circumstance, either by overexpressing the S1P synthesizing kinases (Sphk1, 2) or by repressing of the irreversible degrading lyase (SGPL1)." (PMID 29718989, 2018). "Unexpectedly, patients with both ER+ HER2-positive tumors and high SphK1 were characterized by improved survival and reduced tumor recurrence after tamoxifen treatment." (PMID 29385066, 2018). "HULC was further found to sequester miR-107, a known regulator of E2F1, resulting in a cascade of upregulated E2F1, increased SPHK1 activation, and eventually, tumor angiogenesis." (PMID 30159431, 2017). "Next, SphK1 overexpression in HT-29 enhanced tumor growth as compared to GFP control in nude mice (229.5 mm3 vs. 90.9 mm3, respectively, P < 0.05)." (PMID 28583134, 2017). "For example, HULC was found to promote tumor angiogenesis by upregulating sphingosine kinase 1 (SPHK1), an enzyme that generates sphingosine phosphate, which is known to contribute to cell survival, proliferation, differentiation, and angiogenesis." (PMID 30159431, 2017). "In the current study, we found both MVDCD34 and MVDCD105 were significantly correlated with the levels of SphK1 in tumor tissue." (PMID 29088837, 2017). "Despite this, there was a significant association between proliferative activity (Ki67 staining) and SphK1 expression in both tumor types." (PMID 28778177, 2017). "Blocking SphK1/S1P inhibited the formation of new vasculature and hence deprived the tumor of important nutrients." (PMID 28415564, 2017). "MCF-7 tumor cell-specific overexpression of SPHK1 promoted microvessel density in the periphery of larger tumors with higher frequency in nude mice." (PMID 28804221, 2017). "On the other hand, the liver tumor cells from SPHK1 Tg mice showed nuclear atypia with higher tumor cell density and milder fatty change than wild-type and SPHK1 knockout mice, and these liver tumors were diagnosed as moderately differentiated HCC." (PMID 29208982, 2017). "We found that tumor volume was reduced in SphK1 KO mice as compared to WT mice (14.8 vs. 29.1 mm3, P < 0.05)." (PMID 28583134, 2017). "SphK1/S1P extracellular activity has also been shown to promote oncogenicity through initiation of the formation of new vasculature to support new tumor growth." (PMID 28415564, 2017). "When injected subcutaneously in nude mice, although both GFP control and SphK1 overexpressing HT-29 cells produce tumors, the tumor volume in the SphK1 overexpressing was significantly greater than GFP control cells." (PMID 28583134, 2017). "We first found tumor formation in SphK1 overexpression mice at 18 days after injection, while tumor formation in GFP control mice at 21 days after injection was observed." (PMID 28583134, 2017). "We conclude that miR-124 acts as a tumor suppressor in HNSCC by directly inhibiting SphK1 activity and its downstream signals." (PMID 28212569, 2017). "Sphingosine is phosphorylated into a tumor promoter sphingosine-1-phosphate (Sph-1P), by sphingosine kinase 1 (SPHK1) or 2 (SPHK2)." (PMID 28445970, 2017). "Recently, Hirata and colleagues examined the effects of the transcription factor SphK1 on tumor initiating ability of breast CICs by injecting a small amount (100,000 viable cells) of a CIC-enriched cell population into a mouse xenograft model." (PMID 27086916, 2017).
tumor (continued). "Overexpression of SphK1 has also been seen in both animal and xenograft models of several tumor types including a rat colon adenocarcinomas and a mouse leukemia model, and human breast, lung, and colon tumors, as compared to matched normal tissues." (PMID 29149079, 2017). "In vitro studies suggest that IGFBP-3, which potentiates EGFR signaling via activation of SphK1, is a driver of proliferation in these tumors and its measurement in tumor tissue should be evaluated as a potential biomarker of drug combination efficacy." (PMID 28778177, 2017). "More importantly, SphK1 overexpression in intestinal epithelium significantly increased tumor multiplicity (tumors per mouse) when compared to WT mice." (PMID 28583134, 2017). "Sphingolipid analysis demonstrated that serum S1P level in tumor is higher in SphK1 overexpressed HT-29 cells than in GFP control cells." (PMID 28583134, 2017). "Treatment of tumor-bearing mice with SK1-I (SphK1 inhibitor), decreased S1P levels in both the circulation and in the tumor and significantly decreased the tumor size, angiogenesis and lymphangiogenesis." (PMID 28869494, 2017). "Overexpression of SPHK1 required to transform NIH3T3 fibroblasts to tumor phenotype in nude mice; and also the upregulation of this enzyme is associated with erythroleukemia." (PMID 29531546, 2017). "SPHK1 is known to be up-regulated in many human solid hypoxic tumors and has been suggested to promote tumor vasculogenesis and metastasis." (PMID 27284992, 2016). "This study is an initial investigation into the potentially significant and unrecognized role of SPHK1 in the tumor stroma of HGSC." (PMID 26716409, 2016). "In HGSC cells, overexpression SPHK1 increased tumor cell proliferation, migration, and the development of chemoresistance while its knockdown or pharmacological inhibition resulted in reduced proliferation and enhanced apoptosis in vitro." (PMID 26716409, 2016). "Studies in models of organ fibrosis have provided insight into the potential roles of SPHK1 in tumor stroma." (PMID 26716409, 2016). "In a syngeneic tumor model, administration of the specific sphingosine kinase 1 (SphK1) inhibitor suppresses S1P level, and reduces peritumoral lymphatic density and LN metastases." (PMID 28036019, 2016). "We observed significantly higher expression of SPHK1 mRNA in the tumor samples compared to the benign ovary controls (p=0.0004)." (PMID 26716409, 2016). "Immunohistochemistry (IHC) revealed that the number of stained AHR and SPHK1 cells was reduced in the primary tumor." (PMID 27129165, 2016). "Congruously, ELISA showed that the hemoglobin content in tumor tissues derived from HULC-overexpressed group was higher than that from SPHK1-knockdown group, suggesting that HULC enhances tumor angiogenesis through SPHK1." (PMID 26540633, 2016). "Meanwhile, the silence efficiency of HULC (or SPHK1) was confirmed by qRT-PCR and Western blot analysis in the tumor tissues from mice." (PMID 26540633, 2016). "We demonstrated that in these tumor tissues, the expression of SPHK1 was positively correlated with Ki-67 and p-Akt." (PMID 27811359, 2016). "In summary, the current study suggests a novel role for SPHK1 in the activation and tumor-promoting role of CAFs." (PMID 26716409, 2016). "Sphingosine kinase enzymatic activity assays performed on tumor lysates revealed that while FTY720 significantly reduced SPHK1 activity in tumor cells, the combined treatment was much more effective." (PMID 27811359, 2016). "The importance of stromal SPHK1 in tumorigenesis was confirmed in vivo, by demonstrating a significant reduction of tumor growth and metastasis in SPHK1 knockout mice." (PMID 26716409, 2016). "Targeting of SPHK1 or S1P in pre-clinical mouse models of HGSC was also effective in inhibiting tumor growth." (PMID 26716409, 2016). "Second, SPHK1 inhibition would not only target the tumor stroma, but would also have direct effects on the tumor cells." (PMID 26716409, 2016).
tumor (continued). "Functionally, si-SPHK1 remarkably abolished the HULC-enhanced tumor angiogenesis in vitro and in vivo." (PMID 26540633, 2016). "FTY720 suppressed azoxymethane-induced colonic inflammation in mice and suppressed the subsequent development of tumours by down-regulating SPHK1 and S1PR1, which is important for persistent NF-κB and STAT3 activation, as well as IL-6 production in this model." (PMID 26171944, 2015). "S1P is mainly produced intracellularly by SphK1 and exerts its paracrine/autocrine effects by being secreted into the tumor microenvironment." (PMID 25915662, 2015). "Blocking SPHK1 activity suppressed tumor growth and reduced tumor occurrence and metastasis in nude mice." (PMID 26311741, 2015). "When SPHK1 staining was present, it was invariably present in virtually all tumour cells and we observed minimal variation in the proportion of tumour cells staining positive." (PMID 26493335, 2015). "Nonetheless, genetic studies definitely point to a significant requirement for SPHK1 in tumour growth." (PMID 24970218, 2014). "The observation that SphK1 is overexpressed in all HNSCC stages and is associated with depth of tumor invasion, metastasis and clinical failure underscores the importance of SphK1 in HNSCC pathology." (PMID 25197261, 2014). "SphK1 is known to play a role in tumor progression, resistance to radiochemotherapy, and migration patterns." (PMID 25245676, 2014). "The ability for high potency signalling molecules such as S1P to control host organ responses to the tumour cells appears to be strengthening the case for therapeutics targeting the SPHK1-S1P signalling system." (PMID 24970218, 2014). "SPHK1 is highly expressed in several types of tumor cells (approximately 2–3-fold higher) and its ability to prevent apoptosis has been extensively demonstrated." (PMID 24173614, 2014). "Further studies are needed to verify that high tumour SPHK1 expression translates into elevated tissue S1P levels." (PMID 24970218, 2014). "Four human tumor cell lines were analyzed for their proliferation and survival capacity upon anti-SphK1 targeting with the highly specific SKI-II inhibitor and anti-EGFR targeting with cetuximab." (PMID 25245676, 2014). "Sphingosine kinase-1 (SphK1) is an important enzyme in sphingolipid metabolism which regulates tumor growth in HNSCC." (PMID 25197261, 2014). "On the other hand, silencing SphK1 reduces HNSCC tumor growth and sensitizes tumors to radiation-induced death." (PMID 24970177, 2013). "SphK1 expression also correlated with depth of tumor invasion, lymph node metastasis, and pathological state." (PMID 24970177, 2013). "Paired samples of normal and tumor tissues from ESCC patients showed SphK1 was indeed overexpressed in ESCC when measured both with Western blot and IHC." (PMID 24970177, 2013). "Numerous studies reveal the oncogenic role of SphK1; however, the isoform SphK2 seems to possess not only an overlapping role with SphK1 in promoting tumor development but also an opposing role in inducing apoptosis." (PMID 24286034, 2013). "While SphK1 was found to be a key player in tumor growth, downstream signaling remains to be elucidated." (PMID 24970177, 2013). "The main finding was that silencing SphK1 reduced HNSCC tumor growth and sensitized tumors to radiation-induced death." (PMID 24970177, 2013). "The role of SphK1 in HNSCC is most likely due to increased S1P levels in tumor microenvironments and S1P interaction with various cell surface receptors." (PMID 24970177, 2013). "Using clinical samples, SphK1 overexpression was shown to be higher in SCC samples, and this was associated with depth of tumor invasion, metastasis, and clinical failure." (PMID 24970177, 2013). "In this model, we found inhibition of SphK1 decreases tumor growth, tumor burden, as well as lung metastasis." (PMID 24286034, 2013).
tumor (continued). "SphK1, the SphK isozyme most studied in neoplastic diseases, has been shown to be upregulated in HNSCC with overexpression in advanced stage and recurrent tumors." (PMID 22523710, 2012). "Overexpression of SphK1 offered protection to tumor tissues against anticancer drugs by shifting the ceramide/S1P balance towards the cytoprotective S1P and also by the inhibition of cytochrome c release from mitochondria induced by chemotherapeutic agents." (PMID 23028939, 2012). "Here, we observed inflamed granulamatous tissue lining the diaphragm of mice exposed to MWNT that was significantly suppressed in SphK1 knockout mice, which supports a role for SphK1 in tumor promotion." (PMID 23028939, 2012). "Ample evidence reveals the oncogenic role of SphK1; however, the isoform SphK2 seems to possess not only overlapping role with SphK1 in promoting tumor development but also opposite role in inducing apoptosis." (PMID 21490804, 2011). "Overexpression of SPHK1 facilitates anchorage-independent growth in vitro and leads to tumor formation in SCID mice." (PMID 21936950, 2011). "Among a total of 82 tumor cases examined, high levels of SPHK1 expression were seen in 33 cases (40.2%), whereas 49 cases (59.8%) had low or undetectable levels of SPHK1 expression." (PMID 21625639, 2011). "SPHK1, an oncogenic enzyme, has been found to induce a transforming phenotype in fibroblasts and tumor formation in nude mice." (PMID 21625639, 2011). "Inhibition of SPHK1 using a dominant-negative form of SPHK1 dramatically decreased tumor formation in nude mice." (PMID 20846391, 2010). "Blocking SPHK1 activity by using its inhibitors, such as camptothecin or docetaxel, has been demonstrated to suppress tumor growth and to reduce tumor occurrence and metastases in nude mice." (PMID 20846391, 2010). "Tumor masses and volumes were similar in both sham-treated and castrated animals, and SphK1 activity as well as metastasis dissemination were comparable in both groups." (PMID 19956567, 2009). "As a consequence, the increase in SPHK1 expression in tumour biopsies has been correlated with a significant decrease in survival rate in patients with glioblastoma multiforme." (PMID 17024123, 2006). "SPHK1 may bridge sphingolipid metabolism with tumor immune suppression and represents a potential promising integrated target for metabolically informed immunotherapy strategies." (PMID 41547931, 2026). "Given that dysregulation of sphingolipid metabolism is also present in other hematopoietic malignancies and solid tumors, this novel feedback mechanism may also be applicable to the interaction between SPHK1 and other tumor drivers." (PMID 40221405, 2025). "Dissecting the potential synergy between FAM46C expression and SphK1 inhibition in additional tumor models could reveal whether FAM46C functions through conserved mechanisms across different malignancies or if its tumor-suppressive role is context-dependent." (PMID 40427516, 2025). "SPHK1 expression was significantly elevated in tumor tissues compared to normal adjacent tissues." (PMID 40589755, 2025). "Reduced SphK1 activity contributes to macrophage pyroptosis and tumor suppression." (PMID 41427031, 2025). "Based on these mechanisms, targeting the SphK1/S1P/S1PR2 axis could not only suppress tumor proliferation and angiogenesis but also reverse EMT phenotypes and resistance, providing promising intervention strategies for precise HCC treatment." (PMID 41234914, 2025). "IHC demonstrated elevated levels of SPHK1 protein expression in CRC tumor tissues." (PMID 40589755, 2025). "In addition, the combination of SPHK1/MMP1 knockdown with anti-PD-1 therapy resulted in more pronounced tumor suppression." (PMID 39629135, 2024). "They suggested that inhibition of sphingosine kinase 1 (SPHK1) activity in TME cells along with induction of pyroptosis in TAMs might contribute to the suppression of tumor development." (PMID 38576612, 2024).